CD4 (CD4 molecule)
Diseases named in the same sentence as CD4 in open-access papers (continued):
Sharing a sentence is not in itself a finding about the gene and the disease.
AIDS (continued). "We also found that participants who remained in the HIV infection stage, had higher CD4+ T-cell counts and were free of AIDS-related complications enjoyed significantly better quality of life than other groups." (PMID 41415224, 2025). "This included variables such as Nadir CD4+ T cell count, age, gender, ethnicity, viral load, AIDS, and antiretroviral therapy (ART) status." (PMID 40053000, 2025). "Because of the independent prognostic value of the CD4/CD8 ratio for non-AIDS morbidity and mortality, our results support the early initiation of ART." (PMID 40738892, 2025). "AIDS symptoms develop at higher CD4 percentages in HIV-2 infections (18.2%) compared to HIV-1 patients (8.2%)." (PMID 40687432, 2025). "A prior AIDS diagnosis was present in 16.1% of participants, and the median baseline CD4+ T cell count was 614 cells/mm3." (PMID 41194922, 2025). "HIV, the virus responsible for acquired immunodeficiency syndrome (AIDS), leads to progressive immune system deterioration by targeting CD4+ T lymphocytes." (PMID 40062024, 2025). "WLWH who present with cervical cancer in Botswana often have CD4 counts well above AIDS-defining levels (i.e., >200 cells/mm3); however, they typically remain below that of their counterparts without HIV." (PMID 40099965, 2025). "Excluding the two patients in the AIDS stage, the average CD4+ T lymphocytes count was 759.36 (SD 409.92), and the HIV RNA load had a mean value of 894.37 copies/mL (SD 8285.52)." (PMID 41010651, 2025). "Our study revealed that CD4+ T-cell counts were an independent protective factor against unsuccessful treatment outcomes in patients with AIDS combined with PTB." (PMID 40510348, 2025). "Nonetheless there were significantly lower proportions of senescent CD4+T cells than in Asympt HIV/Leish or in AIDS/VL subjects." (PMID 40096173, 2025). "In terms of prevalence, during the pre-ART era, the prevalence of disseminated NTM (primarily MAC infection) among advanced HIV/AIDS patients with CD4 counts below 50 cells/μl was reported to be between 10% and 30%." (PMID 40176807, 2025). "Acquired immunodeficiency syndrome (AIDS), caused by HIV, is a lethal disorder characterized by viral targeting of CD4+ T lymphocytes, leading to progressive immune collapse." (PMID 41050925, 2025). "An appreciable proportion (2,307; 28.7%) had a very low CD4+ T-cell count (< 200 cells/mm3) at time of diagnosis; this was also the case for those who progressed to AIDS (950; 55.5%) or died/emigrated (1,137; 33.6%)." (PMID 40937553, 2025). "Immunocompromised patients from a variety of medical illnesses or undergoing certain treatments including those with HIV/AIDS and CD4 counts less than 50 are more commonly affected as the virus undergoes reactivation." (PMID 39981470, 2025). "Recent infection data were used to reclassify new HIV diagnoses that were defined as late diagnoses based on low CD4 count < 350 cells/uL or presence of an AIDS-defining event." (PMID 41011735, 2025). "Patients with severe HIV/AIDS with clusters of differentiation 4 (CD4) counts less than 100 are significantly prone to develop multiple OFIs." (PMID 40801018, 2025). "While the device is marketed for HIV/AIDS diagnostics, studies have reported a consistent positive bias in CD4 counts, raising concerns about its precision for clinical management." (PMID 39852084, 2025). "At the time of inclusion in the study group, 47.6% of cohort members had as a first CD4+ cell count less than 350 CD4+ cells/mm3 (46.5% in males, and 51.6% in females), while 9.9% were diagnosed with AIDS." (PMID 40437996, 2025). "This is of paramount importance, as an inverted CD4+/CD8+ ratio is a marker of persistent immune activation and immunosenescence, both associated with an increased risk of non-AIDS-defining comorbidities in older PLWH." (PMID 41305471, 2025).
AIDS (continued). "A proportion of people living with HIV, however, fail to fully restore CD4+ T cell functions or counts, leaving residual immunodeficiency that contributes to non‐AIDS events." (PMID 41190419, 2025). "In individuals with advanced HIV/AIDS, latent tissue cysts of Toxoplasma reactivate because of severe depletion of CD4+ T cells and consequent impairment of IL-12 and IFNγ immune surveillance." (PMID 40559542, 2025). "In PWH off ART, with AIDS, or low CD4+ T cell counts, an expansion of phages and other NHV has been described in the blood." (PMID 41262931, 2025). "We enrolled and followed adults with HIV (CD4 ≤ 350 cells/μL) initiating antiretroviral therapy (ART) at two HIV/AIDS clinics in Uganda from July 2013 to December 2016." (PMID 40169948, 2025). "PWH had had a mean CD4 count of 588.6 cells/mm3, were all on combination antiretroviral therapy (cART), 2 had had an AIDS diagnosis, and 89% (49/55) had been virologically suppressed (HIV viral load <20 copies/mL)." (PMID 40794691, 2025). "Previous studies have shown that PLH with an AIDS diagnosis or very low CD4 counts present lower scores on different HRQoL dimensions, especially physical health and psychological health." (PMID 40369301, 2025). "Given our data and the data demonstrating that people with HIV-2 develop AIDS at higher CD4+ T-cell counts, we recommend close monitoring of CD4+ T-cell counts and clinical events indicating progressive HIV-2 disease in ECs with HIV-2 who are not on therapy." (PMID 40599486, 2025). "Previous studies have also demonstrated that the CD4:CD8 ratio is predictive of non-AIDS morbidity in PWH on ART, highlighting the clinical significance of this parameter." (PMID 39990376, 2025). "HIV is the etiological agent of acquired immunodeficiency syndrome (AIDS), a condition marked by the depletion of CD4+T cells." (PMID 39791742, 2025). "Through a systematic review and meta-analysis, they found that a low CD4/CD8 ratio, particularly values below 0.5, was associated with increased non-AIDS and all-cause mortality risk (OR 3.64; 95% CI 3.04–4.35; I2 = 0.00%)." (PMID 39975671, 2025). "When a patient exhibits a CD4+ T-cell count below 200 cells/μL, he is in the AIDS stage, the most advanced phase of HIV infection." (PMID 40260259, 2025). "In conclusion, sequential point of care testing enables early detection of cryptococcosis and other opportunistic infections in persons with HIV/AIDS and blood CD4 T cell counts ≤200 cells/μl." (PMID 40198673, 2025). "Conversely, apoptosis, a programmed cell death mechanism, is a critical defense mechanism against viral spread and contributes to the depletion of CD4+ T cells, a hallmark of HIV/AIDS progression." (PMID 40072080, 2025). "ART schemes for treating human HIV infections have reduced the HIV viral load in PLWH to undetectable levels and restored CD4+T cell counts to normal levels, significantly reducing AIDS mortality." (PMID 40854952, 2025). "NTM infections are also frequently observed in patients with HIV/AIDS, especially when CD4+ T cell counts fall below 50 cells/μL." (PMID 41356465, 2025). "Although BA has been described to occur in immunocompetent individuals, it predominantly manifests in immunocompromised individuals, especially in patients with HIV and acquired immunodeficiency syndrome (AIDS) presenting with CD4 counts less than 100/mm3." (PMID 39077245, 2024). "The immune status, based on CD4 counts measured close to the diagnosis, was worse among participants with AIDS-defining conditions." (PMID 39476279, 2024). "Non-Caucasian people were 63 (14.79%) of the sample, 96 (22.54%) PLWH had a CD4 nadir below 200 cells/mm3 and 36 (8.45%) had a previous AIDS diagnosis." (PMID 39770548, 2024). "It is important to promote “early diagnosis and treatment of HIV” and regularly monitor CD4 levels in HIV/AIDS to evaluate the efficacy of ART and immune reconstitution, and optimize the ART regimen in time to further reduce the mortality of PWH." (PMID 38778273, 2024).
AIDS (continued). "In AIDS patients, selenium can promote the activation and proliferation of CD4+ T cells, reduce the exhaustion of CD4+ T cells, and decrease HIV viral load." (PMID 38801402, 2024). "CD4 counts at baseline were higher among PLHIV who developed an AIDS event later during follow-up (> 1–3 years: median 153 cells/μL, IQR 40–296, > 3–6 years: median 181 cells/μL, IQR 85–298, > 6 years: median 214 cells/μL, IQR 119–362)." (PMID 38381307, 2024). "This can be attributed to the inclusion of markers associated with these conditions, such as the Fibrosis-4 score for liver disease and CD4 count and viral load for AIDS." (PMID 39015347, 2024). "Still today, this represents a major clinical problem in Europe, as up to 50.4% of patients are diagnosed with AIDS or with CD4+ T-cell count below 350 cells/μl; similar figures are recorded in Italy (57.4–66.2)." (PMID 38704619, 2024). "The relative hazard of AIDS, SNAE/death associated with CD4‐NR was 1.48 (1.09–2.00; p < 0.01) after controlling for key confounders." (PMID 39513741, 2024). "The graph shows the differences in CD4 cell measures of HIV/AIDS patients (both within and across patients)." (PMID 39367327, 2024). "AIDS, caused by HIV, compromises the immune system by primarily targeting CD4+ T lymphocytes, rendering patients more susceptible to opportunistic infections and other health complications." (PMID 39588421, 2024). "Our patient with a CD4+ count of 44 cells/mcL, AIDS stage 3, had an immensely impaired immune system, unable to keep up with the rapid spread of WNV, and causing a seronegative result, specifically a negative CSF and serum WNV IgM and IgG." (PMID 39077811, 2024). "Human Immunodeficiency Virus Type 1 (HIV-1) presents significant challenges to the immune system, predominantly characterized by CD4+ T cell depletion, leading to Acquired Immunodeficiency Syndrome (AIDS)." (PMID 38529284, 2024). "CD4+ cell count in HIV/AIDS patients (Full dataset, CD4+ baseline > 200, baseline CD4+≤ 200) by treatment during follow-up after PSM." (PMID 39240822, 2024). "Association of intestinal parasite prevalence with CD4 count, viral load, and ART status in people living with HIV/AIDS." (PMID 39664543, 2024). "Current literature has documented solitary cerebral lesions linked to a positive Toxoplasma IgG antibody, although, in those studies, patients were often confirmed to have AIDS with CD4 counts as low as 75 cells/mm3." (PMID 39569225, 2024). "This is also reflected in the 33% late diagnoses with advanced immune defect defined as CD4 cell count < 200 CD4 cells/μl or even AIDS (18%) of all HIV diagnoses." (PMID 39476279, 2024). "Among those, 43 (55.8%) had a CD4 cell count of < 200 cells/mm3 and 39 (50.6%) presented with AIDS-related conditions." (PMID 38594292, 2024). "AIDS: When the immune system becomes severely compromised, and the CD4+ T cell count falls below a certain threshold, the condition progresses to AIDS." (PMID 39496030, 2024). "According to the author, all patients with AIDS and reactivation of the disease in the CNS had CD4+ T-lymphocyte count of less than 200 cells, with a high mortality rate." (PMID 39549639, 2024). "A member of the Retroviridae family, HIV is a single-stranded positive-sense RNA virus that infects CD4 helper T-cells and macrophages, leading to the development of acquired immunodeficiency syndrome (AIDS)." (PMID 39522757, 2024). "Several cohort studies have investigated the association between CD4:CD8 ratio and the risk of non-AIDS defining malignancies and other clinical events." (PMID 38092042, 2024). "Impaired CD4 + T cell activation, as seen in conditions like HIV/AIDS, can result in a higher risk of opportunistic infections." (PMID 38280109, 2024). "One study found that immediate initiation of ART in patients with a baseline CD4 cell count ≥ 500 cells/μL can lead to a significant reduction in AIDS-related mortality." (PMID 38778273, 2024).
AIDS (continued). "The hazard of developing ADRs is increased by 41% among HIV/AIDS patients who have baseline CD4 count ≤ 200 cell/μL than those patients who have baseline CD4 count > 200 cell/μL (AHR = 1.41 [1.18, 1.69])." (PMID 38410498, 2024). "Unfortunately, laboratory information on the HIVviral load and CD4+ T cell count for individuals treated in the private healthcarenetwork, as well as data on AIDS-related opportunistic infections, were notavailable." (PMID 39536214, 2024). "The higher incidence of PML in patients with HIV/AIDS and idiopathic CD4+ T-cell lymphopenia underscores the importance of CD4+ T lymphocytes in the pathophysiology of PML." (PMID 39583423, 2024). "Accordingly, different nef alleles from asymptomatic patients were far less capable of downmodulating CD4 compared to those from AIDS patients when both were substituted for the wt nef gene of the HIV-1 X4-tropic NL4.3 virus." (PMID 38787201, 2024). "The World Health Organization (WHO) has recommended LFA—a strategy shown to be cost-effective —for detecting CrAg as screening in AIDS patients with low CD4+ cell count in regions with a prevalence of cryptococcosis greater than 3%." (PMID 39057375, 2024). "HIV progresses to Acquired Immunodeficiency Syndrome (AIDS) when the CD4+ T-cell count decreases substantially (below 200 cells/mm3), leading to the inability of the body to fight off infections and diseases." (PMID 39201495, 2024). "The AIDS-defining diagnosis, along with a CD4 + cell count of 41/μl, suggests a prolonged period of HIV positivity." (PMID 38581028, 2024). "In a past systematic review, the predictors of frailty included older age, comorbidities, diagnosis of acquired immunodeficiency syndrome (AIDS) and low current CD4+ cell count." (PMID 38426187, 2024). "In this study, a mathematical model for the spread of HIV/AIDS through unprotected sexual intercourse has been constructed based on the classification of the number of CD4+ T cells in the body, incorporating the intervention of antiretroviral therapy." (PMID 38665242, 2024). "The replication of HIV-1 induces apoptosis and pyroptosis of CD4+ T cells, and, if untreated, eventually leads to the development of acquired immunodeficiency syndrome (AIDS), opportunistic infections, and cancers." (PMID 39336102, 2024). "We analyze the Korea HIV/AIDS cohort study data to examine the effects of CD4 (cluster of differentiation 4) cell count on the residual life of HIV patients to the onset of dyslipidemia." (PMID 38368350, 2024). "We report two cases of AIDS-related visceral KS affecting the pleura and manifesting with bilateral pleural effusions in two patients with CD4 counts above 200 cells/μL." (PMID 39156295, 2024). "Untreated HIV infection leads to a gradual decrease in CD4+ cell counts, culminating in the development of acquired immunodeficiency syndrome (AIDS)." (PMID 39206043, 2024). "Opportunistic infections (OIs), particularly Pneumocystis pneumonia (PCP) and nocardiosis, are well-recognized complications in individuals with acquired immunodeficiency syndrome (AIDS), especially when CD4 counts drop below 200 cells/mm3." (PMID 39425800, 2024). "Late HIV diagnosis (CD4+ T-cell count < 350 cells/μL, or with an AIDS-defining event) remains a persistent challenge in Greece, indicating potential missed opportunities (MOs) for earlier testing." (PMID 39611208, 2024). "The CD4 T lymphocyte count in people living with HIV (PLHIV) is a predictor for the progression of the disease (AIDS), survival and response to antiretroviral treatment (ART)." (PMID 38478483, 2024). "Historically, individuals living with subtype A viruses exhibit slower CD4 decline and progression to AIDS diagnosis." (PMID 39599821, 2024). "In our study, AIDS diagnosis, higher HIV viral load, older age, and lower CD4 cell count at the time of HIV diagnosis were associated with higher risk of developing active TB disease." (PMID 39257676, 2024).
AIDS (continued). "A plasma virome-based study reported a significant increase in reads belonging to Anelloviruses and HERVs in AIDS patients with CD4 count < 20 cells/μL than HIV-infected patients with CD4 count > 700 cells/μL." (PMID 38751600, 2024). "They found a similar CH prevalence of 28.2%; however, their cohort was notably older, with a median age of 63 years, and only 34.6% had a CD4+ nadir of less than 200 cells/μL, with 17% having a prior AIDS-defining condition." (PMID 38564303, 2024). "Elevated expression of PD-1 on CD8+ and CD4+ T lymphocytes and exhaustion of these cells have been reported in several viral infections, such as lymphocytic choriomeningitis, AIDS, hepatitis B and C." (PMID 38500881, 2024). "Generally, AIDS/HIV patients with a CD4+ cell count higher than 350/mm3 can safely undergo all dental treatments." (PMID 38886374, 2024). "HIV-AIDS patients with a CD4 cell count of less than 200 cells/μL develop progressive, severe disseminated histoplasmosis, often misdiagnosed as TB." (PMID 39194855, 2024). "In this study, MA extract was found to have MIC and MFC and to be able to stop the development of theCandidaspecies that are involved in OC in HIV/AIDS patients with low CD4+ levels:C." (PMID 38387624, 2024). "This approach has been supported bymultiple studies, which highlight the CD4/CD8 ratio as an immuno-stimulatory biomarker indicative of non-AIDS morbidity and chronicinflammation." (PMID 40162460, 2024). "Human immunodeficiency virus (HIV) is predominantly a sexually transmitted infection that destroys CD4+ T lymphocyte cells, while acquired immunodeficiency syndrome (AIDS) is the final disease stage of the original viral infection." (PMID 39398847, 2024). "Analysis of the HIV/AIDS cohort study data reveals dynamic effects of CD4 cell count on the residual life to the onset of dyslipidemia." (PMID 38368350, 2024). "Only bedridden patients who are HIV/AIDS patients experience a statistically significant difference in CD4 cell counts as compared to those who are functionally active." (PMID 39367327, 2024). "The loss of CD4+ T cells, as notably occurs in persons with HIV/AIDS, markedly increases susceptibility to cryptococcosis." (PMID 38712080, 2024). "Untreated HIV infection progresses to an advanced stage known as AIDS, which is characterized by the onset of AIDS-defining illnesses and a CD4 T cell count below 200 cells/mm3." (PMID 39597610, 2024). "The study from Saudi Arabia included 977 subjects and revealed that 20% of HIV positive subjects had a CD4 < 350 at diagnosis, and 50% presented with AIDS at diagnosis." (PMID 38594292, 2024). "VL became a significant opportunistic disease of AIDS, where coinfected patients maintain low CD4+ counts." (PMID 38921748, 2024). "In the present study, the LFA positivity rate was higher in AIDS patients with CD4+ count ≤ 100 cells/mm3, with a predominance in those with ≤50 cells/mm3, but two cases (4.2%) with 101 to 200 cells/mm3 were identified." (PMID 39057375, 2024). "We emphasize thepositive impact of cART on HIV/AIDS treatment, including viral suppression, CD4+cell preservation, and immune function maintenance." (PMID 39052025, 2024). "repeated application of PD-1 inhibitors and chemotherapy resulted in a gradual increase in the number of CD4+ T-lymphocyte, and a complete remission was achieved for relapsed and refractory AIDS-KS." (PMID 39759142, 2024). "In case of HIV infection and AIDS, the maturation of CD4+ cells is inhibited, leading to the reduced expression levels." (PMID 39554636, 2024). "A diagnosis of advanced HIV disease (AHD) is also classified as a CD4 cell count below 200 cells/μL or with an AIDS-defining event at the first follow-up." (PMID 39064161, 2024). "Conversely, Qian Kun Ning effectively reduces mortality and plasma viral load and increases CD4+ T cell counts in patients with HIV/AIDS." (PMID 39175814, 2024).